PDK1 (pyruvate dehydrogenase kinase 1)
Diseases named in the same sentence as PDK1 in open-access papers (continued):
Sharing a sentence is not in itself a finding about the gene and the disease.
adenoma (2 papers, 2015 to 2019). A neoplasm arising from the epithelium. "Adenomas of myeloid cell EP4−/−ApcMin/+ mice had decreased mTOR phosphorylation, in association with decreased expression levels of phosphorylated PI3K, PDK1, AKT and raptor." (PMID 26378024, 2015). "Finally, as observed with the mouse IKKαKO large adenomas, two selected direct HIF-1α target genes (Slc2a1 and PDK1) were also found to be up-regulated by quantitative qRT-PCR in independent IKKαKD H1437 tumor xenografts." (PMID 31792060, 2019).
amyotrophic lateral sclerosis (2 papers, 2013 to 2025). Amyotrophic lateral sclerosis (ALS) is a neurodegenerative disease characterized by progressive muscular paralysis reflecting degeneration of motor neurons in the primary motor cortex, corticospinal tracts, brainstem and spinal cord. "Interestingly, a previous study has shown that cell lines with a known familiar mutation for amyotrophic lateral sclerosis (ALS) have the same expression pattern, with up-regulated PDK1 and down-regulated GLS, as compared to the wild-type cell line." (PMID 23936387, 2013).
autoimmune disease (2 papers, 2020 to 2021). A disorder resulting from loss of function or tissue destruction of an organ or multiple organs, arising from humoral or cellular immune responses of the individual to their own tissue constituents. "Inhibition of excessive ROS could drastically rescue Treg cell survival and alleviate autoimmune diseases, indicating that excessive ROS production was the main reason of PDK1-deficient Treg cell death." (PMID 34646383, 2021).
benign ovarian tumors (2 papers, 2008 to 2021). "PDK1: The expression of immunoreactive PDK1 was present in only 10% of normal ovaries and 60% of benign ovarian tumours." (PMID 18349831, 2008). "Weak staining for PDK1 was observed in one normal ovary and 40% of benign ovarian tumours." (PMID 18349831, 2008). "In the case of benign ovarian tumours, <50% were negative for PDK1 expression, whereas the rest displayed low-to-moderate PDK1 expression confined to the cytoplasm and membranes of the epithelium." (PMID 18349831, 2008).
brain injuries (2 papers, 2019 to 2022). "It has been reported that determine pyruvate dehydrogenase (PDH) is important for the changes in brain energy metabolism seen in various brain injuries, and DCA, a structural analogue of pyruvate, is attached to the pyruvate binding site to inhibit PDK in the order of PDK2 > PDK1, PDK4 > PDK3." (PMID 36432491, 2022).
Cerebral ischemia (2 papers, 2022). Restriction of arterial blood supply to the brain associated with insufficient oxygenation to support the metabolic requirements of the tissue. "Celastrol was found to inhibit the upregulation of HIF-1α and PDK1 induced by cerebral ischemia in the I/R + Celastrol group as compared with the I/R group." (PMID 35035665, 2022).
COVID-19 (2 papers, 2022 to 2023). A disease caused by infection with severe acute respiratory syndrome coronavirus 2. "Among them, six genes (CXCR4, ENO1, FASN, GATA6, PDK1 and TUBB3) have been reported to be associated with the pathological mechanism of COVID-19 and OA." (PMID 37291167, 2023). "CXCR4 and PDK1 involved in the pathogenesis of both COVID-19 and OA." (PMID 37291167, 2023). "By blocking the activity of PDK1, RI173 and other thiuram disulfide or dithiobis-(thioformate) compounds in this series will help diminish SARS-CoV-2 viral replication, which is favorable for COVID-19 treatment." (PMID 35745663, 2022).
epilepsy (2 papers, 2021 to 2022). A brain disorder characterized by episodes of abnormally increased neuronal discharge resulting in transient episodes of sensory or motor neurological dysfunction, or psychic dysfunction. "Here, we report for the first time a disorder caused by a variant in PDK1, which was generally characterized by neurodevelopmental delay and epilepsy." (PMID 36551928, 2022). "Here, we report a de novo heterozygous missense variant in PDK1 (c.1139G > A; p.G380D) in a girl with developmental delay and early onset severe epilepsy." (PMID 36551928, 2022). "We describe a patient with severe epilepsy where genetic analysis showed a de novo missense variant in PDK1, a gene not previously associated with disease." (PMID 36551928, 2022).
Glucose intolerance (2 papers, 2023). Glucose intolerance (GI) can be defined as dysglycemia that comprises both prediabetes and diabetes. "Mice lacking adipose PIK3CA or the downstream kinase PDK1 exhibited glucose intolerance and liver steatosis." (PMID 37311757, 2023).
hemangioma (2 papers, 2017 to 2022). A benign vascular lesion characterized by the formation of capillary-sized or cavernous vascular channels. "PDK1 is enriched in myelomonocytic acute leukemia patients and regulates cell proliferation in hemangiomas." (PMID 35269443, 2022). "PDK1 is over-expressed in most of the cancer cells, and inhibiting the expression of PDK1 followed by decreasing the activity of AKT may become a new treatment strategy for hemangioma." (PMID 28915591, 2017).
HIV-1 infection (2 papers, 2022 to 2023). The type species of lentivirus and the etiologic agent of acquired immunodeficiency syndrome (AIDS). "HIF-1α–activating genes, including HK2, PDK1, and LDHA (which function vitally in the glycolytic pathway), were also up-regulated by HIV-1 infection." (PMID 37798121, 2023).
Huntington disease (2 papers, 2011 to 2023). Huntington disease (HD) is a rare neurodegenerative disorder of the central nervous system characterized by unwanted choreatic movements, behavioral and psychiatric disturbances and dementia. "Altered ERK1/2 and PDK1 phosphorylation have been described in Huntington's disease (HD), characterized by the expression of mutant huntingtin (mhtt) and striatal degeneration." (PMID 22041125, 2011).
Infertility (2 papers, 2020 to 2022). "Another protein kinase, 3-phosphoinositide-dependent protein kinase-1 (PDK1), is crucial for primordial follicle survival in mice, where PDK1 knockout oocytes cause infertility and premature ovarian aging." (PMID 32047242, 2020).
inflammatory bowel disease (2 papers, 2020 to 2023). A spectrum of small and large bowel inflammatory diseases of unknown etiology. "Gerriets and coworkers showed that inhibition of PDK1 using dichloroacetate selectively impairs Th17 proliferation and survival, thereby reducing T-cell-mediated inflammation in inflammatory bowel disease (IBD) and experimental autoimmune encephalitis (EAE) disease models." (PMID 33120978, 2020).
insulinoma (2 papers, 2010 to 2013). "In fact, we silenced PDK1 in clonal insulin–producing insulinoma cells, which lead to enhanced TCA cycle activity and insulin secretion." (PMID 23840896, 2013).
ischemia (2 papers, 2021 to 2022). A hypoperfusion of the BLOOD through an organ or tissue caused by a PATHOLOGIC CONSTRICTION or obstruction of its BLOOD VESSELS, or an absence of BLOOD CIRCULATION. "However, PDK1 protein, an inhibitor of glycolysis, showed increased expression in hind limb tissue both before and after ischemia in KD mice, with a greater increase in ischemic tissue than that in mice in the ND group." (PMID 36038886, 2022). "Additionally, the activation of PDK1-Akt-mTOR-p70S6K reduces injury during ischemia and reperfusion of the liver." (PMID 34064340, 2021).
kidney cancer (2 papers, 2021 to 2022). Primary or metastatic malignant neoplasm involving the kidney. "In kidney cancer cells, PDK1 was found to be upregulated, and upon inhibition, the phosphorylation of the oncogenic AKT pathway was inhibited." (PMID 36076967, 2022). "Inhibition of PDK1 had similar effects as that of miR-375 overexpression on proliferation of A-498 kidney cancer cells." (PMID 33739396, 2021). "Zhou reported that in kidney cancer cells, expression of PDK1 was significantly up-regulated and overexpression of miR-375 in A-498 cells inhibited PDK1 via preventing the phosphorylation of AKT." (PMID 33739396, 2021).
lactic acidosis (2 papers, 2019 to 2026). Metabolic acidosis characterized by the accumulation of lactate in the body. "Metabolomics revealed that stretch-induced mitochondrial dysfunction in PASMCs caused lactic acidosis via enhancement of PDK1 (pyruvate dehydrogenase kinase 1) and c-MYC, leading to increased INHBA expression." (PMID 41568456, 2026). "The PDK1 is a target of the hypoxia-inducible factor (HIF-1), as the HIF-1-mediated expression of PDK1 increases lactic acidosis." (PMID 31434295, 2019).
liver failure (2 papers, 2013 to 2025). A liver disease characterized by the liver losing or has lost all of its function. "Conditional knockout of PDK1 in muscle results in postnatal lethality, with the mice dying within 5–11 weeks of birth due to cardiac defects, while mice lacking PDK1 in the liver die within 4–16 weeks from liver failure." (PMID 23463102, 2013).
lymph node metastasis (2 papers, 2019 to 2021). "Univariate analysis showed that depth of invasion, lymph node metastasis, TNM stage, distant metastasis, UFM1 expression, PDK1 expression, and combined with UFM1 and PDK1 expression were closely related to patient prognosis." (PMID 31533855, 2019). "Moreover, high circ-CNST/LDHA/PDK1 or low miR-578 might predict shorter overall survival, advanced TNM stages, and lymph node metastasis." (PMID 33962616, 2021).
medulloblastoma (2 papers, 2015). A malignant, invasive embryonal neoplasm arising from the cerebellum. "In Medulloblastoma, treatment with the PDK1 inhibitor OSU03012 induced apoptosis in vitro and inhibited xenograft tumor growth." (PMID 25915540, 2015).
metastatic cancer (2 papers, 2015 to 2021). A carcinoma which has spread from the original site of growth to another anatomic site. "The combination of a PDK1 inhibitor and antioxidants might be a better therapeutic approach for metastatic cancer." (PMID 33446631, 2021).
metastatic melanoma (2 papers, 2017 to 2023). A melanoma that has spread from its primary site to another anatomic site. "Mariana Toricelli found that Timp1 confers cell survival through activation of the PDK1 pathway and that Timp1 and AKT cooperate to confer resistance to anoikis in metastatic melanoma cells." (PMID 37626132, 2023). "Our data provides evidence that Timp1 confers cell survival by activating PDK1 signaling pathway and that Timp1 and AKT have synergistic effects to confer anoikis resistance in metastatic melanoma cells." (PMID 28430130, 2017).
ovarian serous adenocarcinoma (2 papers, 2016 to 2021). An adenocarcinoma that arises from the ovary and is characterized by the presence of malignant epithelial cells that, in well differentiated tumors, resemble the epithelium of the fallopian tube or, in poorly differentiated tumors, show anaplastic features and marked nuclear atypia. "Further studies designed to determine the specific mechanism by which sfRon induces high-grade serous ovarian cancer progression, with a strong focus on the role of PDK1 in this process, are warranted." (PMID 27551332, 2016). "The recent discovery of more potent and selective PDK1 inhibitors and Ron inhibitors, and their forthcoming tests in tumor models will be instrumental to understand the significance of sfRon and PDK1 inhibition in high-grade serous ovarian cancer." (PMID 27551332, 2016).
premature ovarian failure (2 papers, 2019). "For example, the ovary-specific deletion of Pten or Pdk1 causes premature ovarian failure despite opposite regulatory roles in the insulin signaling pathway, implying the complexity of the mechanism." (PMID 31009498, 2019).
rhabdomyosarcoma (2 papers, 2007 to 2016). A rare aggressive malignant mesenchymal neoplasm arising from skeletal muscle. "Furthermore, in RC13 rhabdomyosarcoma cells and L6 myocytes, insulin regulates Pi uptake upstream of Akt, which involves activation of PI3K and PDK1." (PMID 27338702, 2016).
thyroid cancer (2 papers, 2013 to 2021). "In human thyroid cancer cell lines, OSU inhibits AKT phosphorylation by PDK1 and leads to an accumulation of the cells in S phase of cell cycle and an induction of apoptosis." (PMID 34356673, 2021).
type 1 diabetes (2 papers, 2020). "The 3‐phosphoinositide‐dependent protein kinase 1 (PDK1)/FoxO1 pathway is important in regulating glucose and energy homeostasis, but little is known about its role in type 1 diabetes‐induced vascular remodelling." (PMID 33108705, 2020). "In this way, plasma insulin level is absolutely deficient in our STZ‐induced type 1 diabetic rats (data not shown), which is consistent with the decreased expression or activity of PDK1 in carotid artery of type 1 diabetic rats in our current study." (PMID 33108705, 2020).
acute renal failure (1 paper, 2015). "As PDK1 is expressed in kidney tubules, it is possible that PDK1 is also involved in the regulation of tubular apoptosis and acute renal failure." (PMID 25950482, 2015).
allergic asthma (1 paper, 2019). A asthma with a basis in a pathological type I hypersensitivity reaction. "Furthermore, activated T cells in patients with allergic asthma produce high levels of lactate correlating to an upregulation of pyruvate dehydrogenase kinase-1 (PDK-1)." (PMID 30917934, 2019).
angiosarcoma (1 paper, 2017). A malignant tumor arising from the endothelial cells of the blood vessels. "At the molecular level, we demonstrated that within one hour of attachment to fibronectin the angiosarcoma cells exhibited enhanced phosphorylation of MAPK/CDK substrates, and reduction in the phosphorylation of PKC and PDK1 substrates." (PMID 29344556, 2017).
Arrhythmia (1 paper, 2015). Any cardiac rhythm other than the normal sinus rhythm. "3-phosphoinositide-dependent protein kinase-1 (PDK1) is involved in the pathogenesis of arrhythmia, and its downstream factor, Forkhead box O1 (Foxo1), negatively regulates the expression of the cardiac sodium channel, Nav1.5." (PMID 25781322, 2015).
asthma (1 paper, 2014). "Chronically activated CD4+ T cells isolated from asthma patients have been shown to overexpress pyruvate dehydrogenase kinase-1 (PDK-1), which results in the production of high levels of lactate which promotes aerobic glycolysis." (PMID 24904823, 2014).
Brugada syndrome (1 paper, 2015). A genetically heterogeneous condition characterized by complete or incomplete right bundle branch block accompanied by ST elevation in leads V1-V3. "In conclusion, through current study we have discovered that the peak Na+ is reduced in PDK1 KO mice and that this may be a cause of sudden death, through mechanisms that have been described for the Brugada Syndrome." (PMID 25781322, 2015). "We would further speculate that PDK1 may be a candidate gene for the Brugada syndrome." (PMID 25781322, 2015).
cervical (1 paper, 2024). "Conversely, switching off metabolic reprogramming mediated by PDK1 abolished the tumorigenicity of TICs, hence contributing to cervical lesion regression." (PMID 39499767, 2024).
cervical tumour (1 paper, 2020). "All these results strongly suggest that HPV16 E6 rescues IRF-1-triggered apoptosis by interfering with the PI3K/PDK1/mTOR signalling pathway in cervical tumour cells." (PMID 33076322, 2020).
Chlamydia infection (1 paper, 2015). "Data from these experiments, in which we used BX-795 as a known inhibitor of PDK1, TBK1, and IKKε, showed significant reductions in early synthesis of IFN-β during Chlamydia infection." (PMID 25798928, 2015).
chronic gastritis (1 paper, 2020). Inflammation of the stomach that is chronic in nature. "The down-regulation of NDUFS8 (NADH: Ubiquinone Oxidoreductase Core Subunit S8), MT2A (Metallothionein 2A), HDAC7 = Histone Deacetylase 7, and PDK1 (Pyruvate dehydrogenase kinase 1) in chronic gastritis and intestinal metaplasia, respectively, was also confirmed." (PMID 31897247, 2020).
chronic hepatitis B (1 paper, 2024). "Consistent with our in vitro findings, in people with chronic hepatitis B there was significantly increased expression of PDK1, PDK2, and PDK3 compared to healthy liver, with a strong trend towards increased expression of LDHA (P =0.057)." (PMID 38655824, 2024).
Cirrhosis (1 paper, 2013). A chronic disorder of the liver in which liver tissue becomes scarred and is partially replaced by regenerative nodules and fibrotic tissue resulting in loss of liver function. "Furthermore, the impaired mTOR signaling under ACM was consistent with the high expression of AMPK and the low expression of PDK1 in DCs and monocytes from patients with advanced cirrhosis." (PMID 24322372, 2013).
cognitive decline (1 paper, 2019). "The results indicated that NMT may improve neuronal apoptosis in VD rats through PI3K/PDK1/AKT pathway, and the activation of PI3K/PDK1/AKT signaling pathway may be an important method for the treatment of cognitive decline." (PMID 30867669, 2019).
dementia (1 paper, 2023). Loss of intellectual abilities interfering with an individual's social and occupational functions. "Lipid supplementation and PDK1 inhibitors are candidates for future studies due to their potential to delay the onset of dementia." (PMID 37958780, 2023).
diabetic cardiomyopathy (1 paper, 2014). Diabetic cardiomyopathy is a disorder of the heart muscle in people with diabetes. "This study demonstrates that over-activation of ROCK2 contributes to diabetic cardiomyopathy by multiple mechanisms, including direct phosphorylation and activation of PKCβ2 and interference with the PDK-1-mediated phosphorylation and activation of AKT and translocation of GLUT4." (PMID 24466133, 2014).
diabetic neuropathy (1 paper, 2023). A chronic, pathological complication associated with diabetes mellitus, where nerve damages are incurred due to diabetic microvascular injury involving small blood vessels that supply these nerves, resulting in peripheral and/or autonomic nerve dysfunction. "The apoptotic-resistance mechanisms of the PDK1-lactic acid axis in Aβ-resistant nerve cells may give us new inspiration to find effective therapy for diabetic neuropathy." (PMID 37935660, 2023). "In this study, we reveal a novel neuroprotective effect of PDK1 in diabetic neuropathy." (PMID 37935660, 2023). "However, the effect of PDK1 on diabetic neuropathy of the central nervous system (CNS) has been ignored until now." (PMID 37935660, 2023).
dilated cardiomyopathy (1 paper, 2011). Cardiomyopathy which is characterized by dilation and contractile dysfunction of the left and right ventricles. "On the other hand, reduction of Akt activity in cardiomyocytes resulting from deletion of its upstream kinase, PDK1, also caused pathological cardiac remodeling (dilated cardiomyopathy and heart enlargement)." (PMID 21559426, 2011).
germ cell tumours (1 paper, 2023). "Six of these genes, including Etv1, Etv4, Ret, Tdgf1, Pdk1 and Calcoco, have been associated with germ cell tumours, stem cells, cell self-renewal, cancer, cell proliferation and cell survival." (PMID 38053127, 2023). "Further examination of the genes that were lower than expected revealed six FGFRi-MEKi DEGs associated with stem cell differentiation, cell self-renewal, cancer, cell proliferation and survival and germ cell tumours, including Etv1 and Etv4, Pdk1, Ret, Tdgf1 and Calcoco2." (PMID 38053127, 2023).
hearing loss (1 paper, 2022). "Other genes were related to BPD-associated outcomes such as retinopathy of prematurity (ROP, e.g., GBP3, FJX1, HIPK2) and hearing loss (e.g., GJB6, TMEM63B) and mitochondrial energy metabolism (e.g., TOMM7, SLC25A26, SLC25A33, PDK1, PKM, MDH1)." (PMID 35484630, 2022).
hepatoblastoma (1 paper, 2024). Hepatoblastoma (HB) is a malignant hepatic tumor and is the most common pediatric liver cancer. "Finally, mutations in CTNNB1, which encodes β-catenin and is found in 70–80% of hepatoblastoma cases, further drive metabolic reprogramming by increasing the expression of pyruvate dehydrogenase kinase 1 (PDK1)." (PMID 39596558, 2024).